CREB3L1 (cAMP responsive element binding protein 3 like 1)
Diseases named in the same sentence as CREB3L1 in open-access papers (continued):
Sharing a sentence is not in itself a finding about the gene and the disease.
cancer (34 papers, 2012 to 2025). A tumor composed of atypical neoplastic, often pleomorphic cells that invade other tissues. "We were particularly interested in the 4 promising drugs which showed more cytotoxic effects towards the more metastatic CREB3L1-deficient HCC1806 TNBC cells since these are typically the most challenging types of cancer cells to treat." (PMID 36123435, 2022). "Interestingly, studies have shown that, similar to Creb3l1, the high expression of Sp1 is associated with poor prognosis in many cancers." (PMID 35803572, 2022). "In addition, our results showed that high CREB3L1 expression was significantly associated with advanced clinical stage in several cancer types." (PMID 36171879, 2022). "Thus, the impact of CREB3L1 expression can be influenced by the genetic background (i.e. gene expression and/or mutational status) of the cancer cells." (PMID 35802566, 2022). "Furthermore, it has been identified that CREB3L1 can function as a prognostic and diagnostic biomarker, and predict the chemotherapeutic responses in some cancer types." (PMID 36171879, 2022). "Furthermore, we also used the XCELL, TIMER, QUANTISEQ, EPIC, IPS and MCPcounter databases to analyze the association between CREB3L1 expression and the infiltrating levels of immune cells in pan-cancer." (PMID 36171879, 2022). "It has been reported that loss of CREB3L1 expression may contribute to or be required for cancer progression and the development of a metastatic phenotype." (PMID 29531016, 2018). "This raises the possibility that loss of CREB3L1 could play a key role in cancer progression and metastasis across a broad group of cancer types." (PMID 26810754, 2016). "Similarly, we also found a significant association between CREB3L1 expression and MSI in nine cancers, which indicated that overexpression of CREB3L1 was positively linked to MSI in COAD, MESO, STAD, and TGCT, and was inversely correlated with MSI in BRCA, CESC, HNSC, KIRC, and LUSC." (PMID 36171879, 2022). "Thus, the impact of CREB3L1 expression may be influenced by the genetic background (i.e. gene expression and/or mutational status) of the cancer cells." (PMID 35802566, 2022). "Furthermore, the univariate Cox regression analysis results showed that CREB3L1 could serve as a protective factor in several cancer types, such as BLCA, KIRC and KIRP, while a risk factor in ACC and PRAD." (PMID 36171879, 2022). "Besides, we analyzed the characteristics of CREB3L1 mutations in pan-cancer." (PMID 36171879, 2022). "The chemotherapeutic agent doxorubicin blocks cancer proliferation via CREB3L1, which is a crucial downstream mediator in PERK-driven metastasis." (PMID 41301006, 2025). "In bulk datasets, GTSE1+ OB cells and CREB3L1+ CB cells were marked by high infiltration in metastatic samples, suggesting that GTSE1+ OB cells and CREB3L1+ CB cells are two metastasis-enrich cancer cells." (PMID 40831537, 2025). "CREB3L1 expression has been reported to be upregulated by endoplasmic reticulum stress, inhibiting cancer cell proliferation and promoting apoptosis." (PMID 39764513, 2024). "It is believed that the CREB3L1 abnormal expression is the key driver of the malignant progression of numerous cancers." (PMID 39015775, 2024). "We further explored the characteristics of CREB3L1 genetic alternations in different cancers by enrolling the TCGA Pan-Cancer Atlas studies in cBioPortal database." (PMID 36171879, 2022). "Then, we also explored the differential CREB3L1 mRNA expression between cancer samples in TCGA and normal tissue samples in GTEx." (PMID 36171879, 2022). "Due to the loss of CREB3L1, ATC cells were unable to activate alpha-smooth muscle actin (α-SMA)-positive cancer-associated fibroblasts (CAFs)." (PMID 36192735, 2022). "The potential relationship between CREB3L1 expression and drug sensitivity in human cancers was also investigated." (PMID 36171879, 2022).
cancer (continued). "The Kaplan-Meier analysis indicated that the CREB3L1 expression levels were correlated with OS in 7 cancers, DSS in 7 cancers, and PFS in six cancers." (PMID 36171879, 2022). "On the contrary, several studies have reported opposite conclusions that CREB3L1 can contribute to cancer cells metastasis and invasion." (PMID 36171879, 2022). "The results revealed that the total alteration rate of CREB3L1 was 1.4% in pan-cancer with various alternation types, such as amplification, miss mutation, and deep deletion, and patients with SKCM has the highest CREB3L1 mutation rate." (PMID 36171879, 2022). "The potential role of CREB3L1 in predicting the immunotherapeutic efficacy in cancer patients was further investigated." (PMID 36171879, 2022). "In this pan-cancer analysis research, we analyzed the expression pattern of CREB3L1 and its relationship with the prognosis of cancer patients." (PMID 36171879, 2022). "The broad interest in these findings lies in Creb3l1's role is to control the UPR pathway foremost as Creb3l1 is being investigated as a target for cancer therapies." (PMID 35803572, 2022). "To identify the prognostic significance of CREB3L1 in cancer patients, we further performed a comprehensive prognosis analysis using the survival data of TCGA pan-cancer dataset, including OS, DFS, DSS and PFS." (PMID 36171879, 2022). "In our study, we confirmed that CREB3L1 is significantly correlated with the sensitivity of several anti-cancer drugs, especially targeted therapy agents, such as cabozantinib, lenvatinib, and dabrafenib." (PMID 36171879, 2022). "Our research provides highlights into the biological functions of CREB3L1 in pan-cancer, and the candidate effect of CREB3L1 in predicting the prognosis and immune-related phenotypes." (PMID 36171879, 2022). "Most TNBCs (75%) have downregulated the expression of CREB3L1 (cAMP-responsive element binding protein 3 like 1), a transcription factor and metastasis suppressor that represses genes that promote cancer progression and metastasis." (PMID 36123435, 2022). "DOX has been shown to inhibit proliferation of cancer cells through proteolytic activation of CREB3L1 (cyclic AMP [cAMP] response element-binding protein 3-like 1), a transcription factor synthesized as a membrane-bound precursor." (PMID 34632049, 2021). "Inhibition of CREB3L1 by genetic or pharmacological methods suppresses cancer cell invasion and metastasis." (PMID 33937330, 2021). "To further confirm the involvement of cell-surface GRP78 and its transcription factor CREB3L1 in the migratory function of cancer cells, we depleted CREB3L1, using CRISPR/Cas9 technology, in the MDAMB231 cell line." (PMID 33042795, 2020). "Collectively, our findings establish CREB3L1 as a promising target downstream of the PERK pathway for therapeutic blockade in cancer." (PMID 29057869, 2017). "Second, we inhibited CREB3L1 expression to test if it was required for the invasiveness of invasive cancer lines." (PMID 29057869, 2017). "Both the full length and truncated form of CREB3L1 were upregulated in invasive cancer cells when compared to non-invasive cells." (PMID 29057869, 2017). "The present findings establish CREB3L1 as a key downstream mediator of PERK’s pro-metastatic function in cancers." (PMID 29057869, 2017). "In this study, we show that this is indeed the case, and identify a key transcription factor (CREB3L1) downstream in the pathway, that specifically functions to promote metastasis in cancer cells that have activated PERK." (PMID 29057869, 2017). "A recent study demonstrated that CREB3L1 expression was required for the chemotherapeutic agent doxorubicin to block the proliferation of cancer cells." (PMID 26810754, 2016). "Cancers of the breast, prostate, kidney (papillary), stomach and pancreas all had generally increased CREB3L1 expression in tumors as compared to the corresponding normal tissue." (PMID 26810754, 2016).
cancer (continued). "In addition, loss of CREB3L1 expression could have prognostic value for multiple forms of cancer." (PMID 26810754, 2016). "In support of a wider role for CREB3L1 in multiple cancer types, we determined that CREB3L1 mRNA expression is altered in many types of cancer." (PMID 26810754, 2016). "And does expression or activation of CREB3L1 correlate with doxorubicin sensitivity across a panel of cancer cell lines, such as the Cancer Cell Line Encyclopedia, or clinical specimens?" (PMID 23256047, 2012). "In the current study, we determine that doxorubicin induces proteolytic activation of CREB3L1, and this cleavage is required for doxorubicin to inhibit proliferation of cancer cells." (PMID 23256041, 2012). "We show that the sensitivity of cellular response to doxorubicin is positively correlated to CREB3L1 expression in cancer cells." (PMID 23256041, 2012). "Importantly, the upregulated expression of CREB3L1 and BCAS1 and downregulated expression of ID1 and ID3 appeared least impacted by the co-existing 2nd (cancer) pathway variants based on visualisation of the heat maps." (PMID 40348815, 2025). "Moreover, CREB3L1 expression was also demonstrated to be imperative for the efficacy of doxorubicin and paclitaxel in blocking the proliferation of cancer cells." (PMID 40427627, 2025). "CREB3L1+ CB cells enriched with genes involved in the extracellular matrix organization pathway, suggesting that cancer cells could leverage extracellular matrix remodeling to create a microenvironment that facilitated metastasis." (PMID 40831537, 2025). "This review summarizes the upstream and downstream regulatory network of CREB3L1 and thoroughly presents our current understanding of CREB3L1 research progress in both physiological and pathological conditions with special focus on the novel findings of CREB3L1 in cancers." (PMID 38164349, 2024). "Suppression of CREB3L1 is conducive to hampering cancer cell invasion and metastasis." (PMID 38164349, 2024). "Nevertheless, multiple involvement of CREB3L1 suggests that it may serve as a candidate target for the treatment of cancers and fibrosis." (PMID 38164349, 2024). "Further analysis of differences in the expression of ZEB1, ZEB2, and CREB3L1, which are included in the GeoMx Cancer Transcriptome Atlas Panel gene list, revealed significant enrichment in Vim+ carcinoma cells relative to that in Vim− carcinoma cells from the nine ROIs." (PMID 39256881, 2024). "Thus, we conducted this first-time and comprehensive investigation to illustrate the roles of CREB3L1 across human cancers." (PMID 36171879, 2022). "Notably, it has been reported that CREB3L1 expression is frequently altered in many cancers, and complex functions and mechanisms of CREB3L1 in cancer development have been clarified in several studies." (PMID 36171879, 2022). "CREB3L1 can be downregulated in these cancers by epigenetic silencing." (PMID 35802566, 2022). "Hence, we further explored the correlation between CREB3L1 expression levels and the abundance of infiltrating immune cells in pan-cancer." (PMID 36171879, 2022). "A significant difference of CREB3L1 expression was detected in 25 cancer types." (PMID 36171879, 2022). "The results suggested that CREB3L1 might effectively predict the efficacy of PD-1/PD-LI inhibitors treatment in some specific cancer types." (PMID 36171879, 2022). "Moreover, CREB3L1 had promising applications in predicting the immunotherapeutic benefits and drug sensitivity in cancer management." (PMID 36171879, 2022). "Additionally, numerous ATC cancer cells expressed both CREB3L1 and the fibroblast marker FAP, indicating ATC cells possessed a CAF-like phenotype." (PMID 36192735, 2022). "Furthermore, Gene Set Enrichment Analysis (GSEA) was conducted to explore the potential biological functions and downstream pathways of CREB3L1 in different human cancers." (PMID 36171879, 2022).
cancer (continued). "In addition, KEGG analysis revealed that regulation of autophagy was the most common signaling pathway of CREB3L1 participating in multiple cancer types, including UCEC, LGG, GBM and ESCA." (PMID 36171879, 2022). "Besides, the putative copy-number alterations of CREB3L1 from genomic identification of significant targets in cancer (GISTIC) included many types, such as amplification, deep deletion and gain function, resulting in the alternations of gene expression." (PMID 36171879, 2022). "We also evaluated CREB3L1 expression in pan-cancer, which was ranked from high to low." (PMID 36171879, 2022). "Besides, regulation of autophagy was identified as the most common signaling pathway modulated by CREB3L1 in pan-cancer." (PMID 36171879, 2022). "The results suggested that CREB3L1 might exert various biological functions, especially immune modulatory functions in cancers, including the activation of innate immune response in CESC and adaptive immune response in LIHC, LUSC, PCPG." (PMID 36171879, 2022). "The heterogeneous expression levels of CREB3L1 in OC patients prompted us to examine both baseline expression and nuclear translocation of CREB3L1 in CD45-negative cancer cells after treatment with DOX, OVV, and a combination of OVV followed by DOX using clinical biopsies." (PMID 34632049, 2021). "CREB3L1 can regulate the FAK signaling during cancer cell migration and invasion." (PMID 34746012, 2021). "CREB3L1 expression is frequently altered in many cancer types suggesting that it could have a broader role in cancer progression and metastasis." (PMID 29531016, 2018). "Down-regulation of CREB3L1 gene has been found in two cancer types." (PMID 29531016, 2018). "Our data now supports the investigation of both Nr4a1 and Creb3l1 in cancer studies." (PMID 29311806, 2017). "CREB3L1 was the only transcription factor among the cancer-specific PERK genes we identified." (PMID 29057869, 2017). "Taken together, this study provides a novel mechanism of Creb3l1 activation by Nr4a1 that adds important understanding to transcriptional mechanisms not only in the hypothalamus but also possibly more broadly within cancer research." (PMID 29311806, 2017). "The analysis suggested that CREB3L1 might regulate ECM production and remodeling (p < 10−5, hypergeometric test), key processes associated with cancer cell invasion." (PMID 29057869, 2017). "We next used three approaches to assess if CREB3L1 was required for cancer cell invasion." (PMID 29057869, 2017). "The identification of Nr4a1 as a transcription factor of the Creb3l1 gene may have importance in cancer research." (PMID 29311806, 2017). "The discovery that CREB3L1 expression is frequently altered in many cancer types suggests it could have a broad role in cancer progression and metastasis." (PMID 26810754, 2016). "We also highlight that CREB3L1 expression is frequently altered in many cancer types suggesting that it could have a broader role in cancer progression and metastasis." (PMID 26810754, 2016). "Nevertheless, the mechanism of the down regulation of CREB3L1 in cancer cells remains elusive." (PMID 27121396, 2016). "Owing to the lack of selection pressure against expression of CREB3L1, most cancer cells may still express functional CREB3L1." (PMID 23256041, 2012). "If proteolytic activation of CREB3L1 is required for doxorubicin to inhibit cell proliferation, then the amount of CREB3L1 expressed in cancer cells may determine their sensitivity to doxorubicin." (PMID 23256041, 2012). "Furthermore, ligand–receptor analysis showed preferential interactions of C5AR1-RPS19 and CD74-MIF pairs between GTSE1+ OB cells and CREB3L1+ CB cells in metastasis, which could promote cancer cell growth and metastasis." (PMID 40831537, 2025).
cancer (continued). "Hence, we further investigated the relationship of CREB3L1 expression levels with TMB and MSI in pan-cancer, thereby speculating the potential role of CREB3L1 as a promising predictor for the immunotherapeutic efficacy in a specific cancer type." (PMID 36171879, 2022). "Besides, the Kaplan–Meier survival showed that high CREB3L1 expression was significantly correlated with poor OS and DSS in KIRP, MESO, and SKCM, while was related to better OS and DSS in ACC, suggesting the prognostic significance of CREB3L1 in different human cancers." (PMID 36171879, 2022). "Hence, we deduced that CREB3L1 may play critical roles in cancer immunotherapies, and influence the immunotherapeutic efficacy." (PMID 36171879, 2022). "Now, writing in eLife, Brey Denard, Ching Lee and Jin Ye provide evidence that doxorubicin, a widely used cancer drug, induces cellular toxicity via a novel mechanism that involves the synthesis of ceramide followed by activation of a transcription factor called CREB3L1." (PMID 23256047, 2012). "Thus, more effective chemotherapeutic reagents against cancers may be generated by development of compounds that specifically activate CREB3L1." (PMID 23256041, 2012). "Our study presented evidence for the possible relationship of CREB3L1 expression with MSI and TMB in different cancers." (PMID 36171879, 2022). "Correlations were observed between CREB3L1 expression and several immune biomarkers such as CD28, CXCR4 and KDR in several cancers." (PMID 36171879, 2022). "The univariate Cox regression analysis were performed and found CREB3L1 expression levels were correlated with OS in 11 cancers, DFS in two cancers, DSS in 10 cancers, and PFS in six cancers." (PMID 36171879, 2022). "CREB3L1 expression was also correlated with the expression of multiple immune-related biomolecules, TMB, and MSI in several cancers." (PMID 36171879, 2022). "CREB3L1 expression in ATC cells facilitated IL-1α-mediated CAFs differentiation, thereby remodeling the cancer niche." (PMID 36192735, 2022). "Moreover, a heatmap depicting ZEB1, ZEB2, CREB3L1, and CDH1 across the nine ROIs revealed clear segregation between Vim+ and Vim− carcinoma cells." (PMID 39256881, 2024). "Besides, chemokine signal pathway (in UCS, THCA, PCPG, LAML, and KIRP), pathway in cancer (in THYM, PCPG, and OV) and drug metabolism (in SKCM, LGG, and ACC) were also potential signaling pathways modulated by CREB3L1 in pan-cancer." (PMID 36171879, 2022). "Notably, we found that both cancer cells and CAFs had high expression of FAP and CREB3L1 in ATC tissues." (PMID 36192735, 2022). "Notably, recent studies have reported CREB3L1, a critical member of CREB3 family, participate in cancer initiation and progression, and can serve as a promising clinical biomarker for cancer patients." (PMID 36171879, 2022). "This CREB3L1-mediated signaling program is specifically activated in breast cancer cells when compared to their normal counterparts, representing a non-stress-dependent mechanism of the PERK branch of the ISR in cancer metastasis." (PMID 34746012, 2021). "CREB3L1 acts downstream of PERK, specifically in the mesenchymal subtype of triple-negative tumors, and its inhibition by genetic or pharmacological methods suppresses cancer cell invasion and metastasis." (PMID 29057869, 2017). "No connection has currently been made between Nr4a1 and Creb3l1 expression in cancer cells, but there are studies that support this concept." (PMID 29311806, 2017). "It is also possible that deletions of VGF and TK genes, which are essential for replication of OVV in normal cells but not in cancer cells, influence the nuclear translocation of CREB3L1, which could also vary in different cancer cells." (PMID 34632049, 2021). "The crucial role for CREB3L1 in inhibiting cell proliferation in response to DOX prompted us to examine whether activation of this transcription factor is involved during the induction of ICD by DOX and OVV in cancer cells." (PMID 34632049, 2021).